MITF (melanocyte inducing transcription factor)
Diseases named in the same sentence as MITF in open-access papers (continued):
Sharing a sentence is not in itself a finding about the gene and the disease.
tumor (continued). "Combining fate mapping with live imaging, immunohistochemistry (IHC) and MIHC, we provide direct evidence for the contribution of cells at the MRD site to tumour recurrence, whilst simultaneously demonstrating their MITF-independent to Mitfa+ cell state shift." (PMID 35929478, 2022). "To further reinforce the association between loss of MITF and resistance to MAPK inhibition, we used tumor data from 21 patients treated with BRAF inhibitors alone where transcriptomic data were obtained on available 50 pre- and postrelapse tumors." (PMID 36040798, 2022). "Fluctuating MITF activity during tumorigenesis and tumor progression confounds the ability to define its oncogenic role." (PMID 36497341, 2022). "Goding and co-workers reported that the level of MITF induces different states of melanocytes: maintenance of differentiation (MITF-high), proliferation (MITF-intermediate) or slow-proliferative and invasive cells with tumor-initiating properties (MITF-low)." (PMID 35631574, 2022). "MITF has recently been reported to be involved in GIST cell survival, proliferation, and tumor growth, and MITF silencing leads to an ETV1 reduction." (PMID 36551682, 2022). "Previously, our group reported that silencing of the adaptor molecule SH3 Binding Protein 2 (SH3BP2) downregulated KIT and PDGFRA and microphthalmia-associated transcription factor (MITF) levels and reduced tumor growth." (PMID 36551682, 2022). "To investigate how MITF regulates tumor progression in ccRCC, we established two ccRCC cell lines (SNU1272 and Caki-2) with stable MITF knockdown (pLKO.1-shCtrl or pLKO.1-shMITF)." (PMID 34208068, 2021). "The results indicate that MITF shapes the anti-tumor immune response; MITF-KO cells are targeted preferentially by the innate immune response, whereas MITF-expressing cells are primarily targeted by T-cells." (PMID 33789714, 2021). "Since ADAM10-KO cells exhibit high levels of NKG2D ligands, they will be efficiently targeted by NK-mediated cell killing, while maintenance of MITF expression will facilitate a T-cell-mediated anti-tumor response." (PMID 33789714, 2021). "When plotting MITF against CD8 mRNA levels we found three tumor specimens clustered on the left side of the plot." (PMID 34210820, 2021). "Hint1 exerts its tumor suppressor activity by binding to transcription factors, such as MITF and β-catenin, and its suppressive function is in turn regulated by an acetylation-dependent mechanism." (PMID 33671384, 2021). "In this context, MiTF-mediated FANC protein expression appears to be a requirement to cope with the high replication activity of tumour cells." (PMID 33441180, 2021). "Significantly, MITF expression is transcriptionally and translationally suppressed by several microenvironmental signals such that MITFLow cells adopt an invasive, tumor-initiating and drug and immunotherapy-resistant state." (PMID 33789714, 2021). "Immunohistochemistry (IHC) staining revealed that the expression of MITF and KI-67, a marker of cell proliferation, had increased in the tumor tissue derived from MITF overexpression cells, compared with the control." (PMID 34208068, 2021). "Taken together, the results indicate that MITF expression can promote the evasion of NK cell-driven tumor immunity through the proteolytic activity of ADAM10 on NKG2D ligands." (PMID 33789714, 2021). "SA-49, a new novel aloperine derivative, induced MITF-dependent lysosomal degradation of PD-L1 and suppressed Lewis tumor xenograft growth by activating immune microenvironment in C57BL/6 mice." (PMID 34895234, 2021). "Accordingly, the siRNA-mediated silencing of a FANC protein (FANCA or FANCD2) was sufficient to slow tumour growth, even when MiTF overexpression was maintained." (PMID 33441180, 2021).
tumor (continued). "MITF contributed to cell proliferation, migration, invasion and tumor growth in ccRCC through activation of the RhoA/YAP signaling pathways." (PMID 34208068, 2021). "Together, MITF and IFNγ modulate the oscillation of cell states with constant shifts in cell phenotype of the tumor population to develop immunotherapy resistance." (PMID 33329751, 2020). "MITF-induced secretome under BRAFi treatment includes the secretion of ET-1, which supports tumor growth by reactivating the ERK pathway in a paracrine manner." (PMID 32466585, 2020). "In this model, an excess of low-affinity sites will reduce the effective concentration of MITF that is free to recognize the productive binding sites that support melanocyte development and tumor formation." (PMID 32531202, 2020). "Signals in the tumor microenvironmental, such as hypoxia, nutrient availability and cytokines, that dampen MITF levels, can also favor the phenotypic transition." (PMID 33276788, 2020). "The primary finding of our study was that MITF increased tumor cell motility and invasion by modulating MCAM, thus promoting the progression of OvCa." (PMID 33371469, 2020). "Representative IHC images from patients with advanced OvCa showed elevated MITF expression in tumor cells, while low MITF expression was observed in patients with early-stage OvCa." (PMID 33371469, 2020). "MITF expression was found in all samples, and expression levels varied according to tumor characteristics, including clinical stage." (PMID 33371469, 2020). "To assess specific changes in the mesenchymal WM266‐4 populations, we FACS‐sorted these from homogeneous or heterogeneous tumours and found that MITF expression was similar under both conditions." (PMID 32145051, 2020). "In tumours, this resulted in melanocytic phenotype cells that still expressed high levels of MITF, but had up‐regulated EMT and invasive signatures and corresponding transcription factors such as TEAD1 and AP1 factors." (PMID 32145051, 2020). "Intriguingly, while this upregulation is found in tumours from patients on treatment with MAPKi, other studies report reduction of MITF RNA levels in response to MAPKi." (PMID 30277012, 2019). "This cellular reprogramming was characterized by an up-regulation of ATM, MLH1, MCL1 and MITF, genes known to be involved in DNA repair, cell survival and proliferation - essential pathways for tumor survival under stressful conditions like chemotherapy." (PMID 31597943, 2019). "It was observed that MITF is also regulated by miRNAs such as miR‐182 and miR‐137 which directly target MITF, leading to extracellular matrix degradation and, consequently, tumor cell migration and invasion." (PMID 30499222, 2019). "Immunohistochemical examination of 10 distinct tumors showed that in most of the tumors, Tomato+ tumor cells express melanocytic markers Dct and MITF, neuronal markers Nestin, Tubb3 and Gfap, mesenchymal marker Pdgfra and proliferation marker Ki67." (PMID 31685822, 2019). "Low‐MITF populations such as some cell lines or slightly pigmented areas of tumours presumably utilize other proteins to maintain proliferation." (PMID 29369499, 2018). "Specifically, tumours with both BRAF mutation and MITF activation were more sensitive to PLX4720 than tumours with BRAF mutation without MITF activation." (PMID 29950679, 2018). "The in vitro and in vivo data demonstrate that the induction of CRYAB is a major effector involved in the tumor-suppressive activity of the transcription factor MITF in PCa." (PMID 30310055, 2018). "It is thus highly desirable to understand precisely the mechanisms which MITF plays in modulating tumour cell invasiveness, plasticity, migration, proliferation and metastasis in vitro and in vivo." (PMID 29369499, 2018).
tumor (continued). "Previous studies have shown that MITF-low cells reside at the leading edge of a tumor allowing for dissemination from the primary site." (PMID 28545079, 2017). "Based on these considerations, the aim of our work was to confirm in a larger cohort of patients the diagnostic performance of PAX3d, MITF-m and TGFB2 circulating tumor transcripts for CMM detection." (PMID 29156734, 2017). "Similar to what we observed with bosentan, BRAF inhibitor/BQ788‐treated tumours displayed increased expression of MITF and EDNRB." (PMID 28606996, 2017). "We have shown recently that in ~80% of patients on treatment with MAPK inhibitors bulk‐tumour MITF mRNA increases due to transcriptional up‐regulation." (PMID 28606996, 2017). "Depletion of MITF or BRN2 from established tumors of MM649 cells (MITFhigh) resulted in an initial reduction in tumor volume of both shBRN2 and shMITF expressing tumors." (PMID 28883623, 2017). "Depletion of MITF resulted in a cell population that had a slowed cell cycle progression, was less invasive in vitro and had hindered tumor and metastasis forming ability in mouse xenograft studies." (PMID 28883623, 2017). "Again we found that while MITF was up‐regulated in BRAF inhibitor‐responding tumours, its expression was heterogeneous throughout, and strong and weak MITF‐expressing cells were detectable (Fig EV1B)." (PMID 28606996, 2017). "In the phenotype switching model, cells that express BRN2 are the invasive and motile cells within the primary tumor while MITF-positive cells are proliferative." (PMID 28883623, 2017). "The reduced ERK activity in BRAF inhibitor‐treated tumours correlated with increased MITF and EDN1 expression." (PMID 28606996, 2017). "Each specimen was examined by qRT-PCR analysis for the expression of 3 tumor-related transcripts (PAX3d, MITF-m and TGFB2) at diagnosis, and at the following 6 and 12 months during clinical monitoring." (PMID 29156734, 2017). "Role of microRNA-182 in posterior uveal melanoma: regulation of tumor development through MITF, BCL2 and cyclin D2." (PMID 32309578, 2016). "The proposed dual function of TrkA in MM, acting in an oncogenic or in a tumor suppressor like mode, is similar to that of the melanocyte-specific protein MITF, which acts downstream to MAPK." (PMID 26496938, 2015). "Sox10 haploinsufficiency in mice can lead to tumour regression in an already established nevus, and in zebrafish, turning off MITF activity in an established melanoma leads to rapid tumour regression." (PMID 25670789, 2015). "Argani and Ladanyi have proposed regrouping these neoplasms into the category of MiTF/TFE family translocation carcinomas." (PMID 26415891, 2015). "Several studies have shown that reduction in MITF expression reduces xenograft growth, but others found that it increases tumour volume." (PMID 25818589, 2015). "One seemingly paradoxical observation from our study and previous investigations is that although CITED1 behaves as a negative regulator of MITF, both their expression levels appear positively correlated across cells lines and tumours." (PMID 25755924, 2015). "Hypoxia-inducible factor HIF1α was also reported to be a transcriptional target of MITF, and its expression is apparently stimulated by MITF with the well-known consequences of stimulating tumor survival, angiogenesis, and metastases." (PMID 24743024, 2014). "MITF-depleted cells have a more stem cell-like phenotype, increased plasticity, and reduced proliferation, which collectively favor tumor progression, whereas high levels of MITF promote proliferation and differentiation." (PMID 25538895, 2014). "The MiTF/TFE neoplasms have in common the overexpression of MiTF and/or TFE3 or TFEB transcription factors - a subfamily in the helix-loop-helix family of transcription factors." (PMID 24735727, 2014). "We show that PAX3 and MITF immunolabeling can be used to identify melanocytes as well as melanocytic transformed cells within a tumor bulk." (PMID 22747534, 2012).
tumor (continued). "Insufficiently high or low expression of MITF results in tumor-protective differentiation, cell cycle arrest, and subsequent apoptosis." (PMID 22007305, 2011). "Defining the muscle mediated signaling pathways that lead to MiTF downregulation will be of key importance in the identification of the factors responsible for muscle mediated tumor growth inhibition." (PMID 20174581, 2010). "The inverse correlation between MITF and HIF1a was also observed upon application of our signature to independent tumour data suggesting it is a biologically relevant in vivo." (PMID 20041153, 2009). "The neoplasm was immunoreactive for Melan-A, MITF, and S-100 protein indicating melanocytic lineage of the tumor cells." (PMID 18638402, 2008). "Collectively, this study highlights the role of MITF as a genome maintenance factor beyond the melanocyte lineage, which might contribute to the tumor suppressive function of MITF." (PMID 42268265, 2026). "(ii) Genomic profile variations: Individual tumor cells may follow different regulatory models (i.e., linear, sigmoidal, or saturated) based on unique genomic profiles, influencing MITF responses and defining specific tumor phenotypes." (PMID 40458894, 2025). "Notably, silencing or inhibiting MITF has been shown to suppress tumor growth both in vitro and in vivo." (PMID 41168571, 2025). "As KIT-containing exosomes promote GIST invasion and have therapeutic relevance, these results suggest MITF may modulate tumor progression via EV-mediated KIT signaling." (PMID 41168571, 2025). "Notably, MITF protein expression in tumor cells is almost always greater than 50% when TIL falls within the BRISK B category." (PMID 39976551, 2025). "Remarkably, suppression of MITF expression led to reduced tumor size and enhanced T-cell activity." (PMID 40894019, 2025). "Interestingly, we noted an increase in copy number of the part of chromosome 3p encompassing the MITF gene locus only in the tumour tissues." (PMID 41168392, 2025). "Consequently, low SOX10 expression leads to a low MITF expression, retaining the tumor in the mesenchymal phenotype." (PMID 40458894, 2025). "This MITF-to-MYC transition may represent a key oncogenic program that supports tumor growth, promotes adaptive survival, and contributes to resistance to targeted therapy." (PMID 40558540, 2025). "Nevertheless, it should be noted that this apparent co-expression may be the result of bulk RNA analysis, since it was observed that BRN2- and MITF-expressing tumor cells can coexist in the same tumor sample." (PMID 41465101, 2025). "Our results suggest that PTX may promote tumor cell differentiation through modulation of MITF expression, a mechanism that could contribute to its antitumor effects observed in vivo." (PMID 40806647, 2025). "scRNA-seq studies of cells from the primary tumour, residual disease site and the recurrent tumour have shown that MITF-dependent and MITF-independent cells co-exist in the primary tumour, and that MITF-independent cells survive in the residual disease site and contribute to recurrent disease." (PMID 39092608, 2024). "It is hypothesized that the TFE3 fusion proteins function like MITF in the neoplasms, and thus activate cathepsin K expression which can be detected by IHC." (PMID 37218666, 2024). "MITF+ tumor cells showed the most significant inverse correlation with CD8+ T cells." (PMID 39697983, 2024). "In colon cancer and melanoma cells, deacetylation by SIRT1 promotes tumor suppressor activity by enhancing the ability of histidine triad nucleotide-binding protein 1 (HINT1) to bind to β-catenin or MITF, resulting in an increase in the tumor suppressor function of HINT1123." (PMID 39479446, 2024). "Furthermore, MITF is a critical survival factor for melanoma and modulates the response to targeted tumor inhibitors." (PMID 36812891, 2023).
tumor (continued). "We will study the mechanism underlying the synergistic effect of α-Mangostin with chemotherapies, and clarify whether α-Mangostin mediates down-regulation of MITF for anti-tumor effect." (PMID 37575275, 2023). "In addition to its role in the development of tumor resistance, MITF acts as a master regulator of melanocyte differentiation through the upregulation of receptor tyrosine kinases (RTKs) including the AXL, EGFR, and PDGFRβ." (PMID 37370757, 2023). "MITF expression was moderately positive in normal renal tissues (no glomerular cells were detected, and moderate staining was found in the renal collecting duct and distal tubules), but weakly positive in tumor tissues using the CAB002578 antibody." (PMID 37056387, 2023). "Thus, SH3BP2 silencing decreased oncogenic KIT/PDGFRA levels, reduced MITF levels, led to apoptosis in vitro, and decreased tumor growth in vivo." (PMID 36834926, 2023). "However, basal MITF expression remains high in the hypoxic tumor microenvironment because of the amplification of MITF itself or other alterations in its upstream regulators." (PMID 36901857, 2023). "Notably, MITF has been reported as a tumour suppressor in inhibiting tumour growth and metastasis in GC." (PMID 36268034, 2022). "Moreover, well-known target proteins of MITF in melanogenesis such as TYRP1, DCT, and TYR1 proteins were positivity regulated in Opn4WT tumor, and therefore, strongly suggest a reduction of MITF signaling in Opn4KO tumor." (PMID 35562405, 2022). "MITF promotes tumor cell survival by targeting target genes to make them resistant to chemotherapy." (PMID 35893303, 2022). "However, both MITF-low and MITF-high cells can give rise to tumours, which then contain both types of cells." (PMID 35682684, 2022). "They found a negative association between MITF staining and tumour pigmentation but a positive correlation between MITF staining and proliferative activity." (PMID 35682684, 2022). "Furthermore, MITF activity depends on tumor microenvironment (TME) conditions, such as nutrient depletion, immune surveillance and inflammation, heterotypic interactions with normal cells, hypoxia, extracellular matrix (ECM) composition, and drug treatment." (PMID 36497341, 2022). "In addition to transcriptional and post-transcriptional regulation of MITF expression, regulation of MITF activity contributes to its function in tumours." (PMID 36268034, 2022). "Three major subpopulations of cells with different MITF expression levels have been detected in CM, some with high MITF levels, which were more proliferative, some exhibiting low MITF levels along with higher invasive and tumor‐forming capacities, and others expressing markers of both signatures." (PMID 34080276, 2022). "Apart from this, we also employed the B16F10 xenograft tumor model to test whether targeting MITF could enhance the effectiveness of anti-PD-1 antibodies via ferroptosis." (PMID 36429010, 2022). "In addition, upregulation of MITF rescued the dampened tumour proliferative/metastatic properties driven by shRNA-mediated silencing of CREB1." (PMID 36268034, 2022). "The intersection of the MITF pathway and the interferon-gamma pathway was observed in the tumor intermediate state, which promoted tumor cells to be recognized by CD8+ T cells and might be the cause of the crosstalk propensity." (PMID 35903095, 2022). "Furthermore, EP300 encodes the histone acetyltransferase paralogue p300 that manipulates different cellular processes (e.g., proliferation, apoptosis, and DNA repair) and promotes tumor growth through its downstream oncogene target MITF." (PMID 36125617, 2022). "In the resistant stage, some tumours retained high MITF levels, while others displayed lower MITF levels; accordingly, it would be interesting to analyse whether MITF and ROCK-p-MLC2 correlate in this setting." (PMID 35159327, 2022).